PHLDA3 (pleckstrin homology like domain family A member 3)
Diseases named in the same sentence as PHLDA3 in open-access papers (continued):
Sharing a sentence is not in itself a finding about the gene and the disease.
diabetes (1 paper, 2019). "Our studies suggest that Phlda3 expression may be beneficial for preserving beta cell mass during the pathogenesis of diabetes." (PMID 31492921, 2019). "However, whether Phlda3 expression is altered in diabetes or plays a role in beta cell pathophysiology are unclear." (PMID 31492921, 2019). "We first assessed whether the Phlda3 expression is altered in diabetes." (PMID 31492921, 2019).
esophageal NETs (1 paper, 2020). "Analysis of the function of PHLDA3 in other types of NETs including pituitary NETs, esophageal NETs, thyroid NETs, and parathyroid NETs will be important in future studies." (PMID 32521808, 2020).
gastric cancer (1 paper, 2024). A primary or metastatic malignant neoplasm involving the stomach. "Surprisingly, the Oncomine database revealed elevated PHLDA3 levels in gastric cancer depending on the samples and relevant studies analyzed." (PMID 38921000, 2024). "The oncogenic role of PHLDA3 was upregulated in gastric cancer." (PMID 38921000, 2024). "Nevertheless, PHLDA3 could play an oncogenic role in gastric cancer." (PMID 38921000, 2024). "Additionally, PHLDA3 may be a useful therapeutic target for ovarian, renal, and gastric cancer." (PMID 38921000, 2024).
head and neck squamous cell carcinoma (1 paper, 2024). A squamous cell carcinoma that arises from any of the following anatomic sites: lip and oral cavity, nasal cavity, paranasal sinuses, pharynx, larynx, and salivary glands. "According to a recent study, the negative feedback regulators of the PI3K pathway act as tumor suppressors and PHLDA3 is a negative feedback regulator of the PI3K pathway of head and neck squamous cell carcinoma (HNSC)." (PMID 38921000, 2024).
heart failure (1 paper, 2024). Inability of the heart to pump blood at an adequate rate to meet tissue metabolic requirements. "The prognosis of cardiovascular diseases can be improved in cases of PHLDA3 deficiency, suggesting that it may play a role in heart failure and pathological cardiac hypertrophy." (PMID 38921000, 2024). "However, it is still unknown how PHLDA3 affects heart failure and pathological cardiac hypertrophy." (PMID 38921000, 2024).
insulinomas (1 paper, 2026). "However, PHLDA3 mutations have not previously been investigated in radiation-induced insulinoma cell lines, even though ionizing radiation is known to cause genetic abnormalities." (PMID 42220659, 2026).
keloid (1 paper, 2025). An irregularly shaped, elevated mark on the skin caused by deposits of excessive amounts of collagen during wound healing. "Increased expression of both PHLDA3 in not sun-exposed skin (p = 1.74 × 10-14, OR = 2.39 [1.91 – 2.99]) and NEDD4 in fibroblasts (p = 5.90 × 10-11, OR = 1.91 [1.57 – 2.31]) were associated with increased risk of keloids." (PMID 40835838, 2025).
large cell neuroendocrine carcinoma (1 paper, 2025). A usually aggressive carcinoma composed of large malignant cells which display neuroendocrine characteristics. "Interestingly, our analysis of large-cell neuroendocrine carcinoma (LCNEC) samples revealed that loss of PTEN and PHLDA3 often occurs in the same tumors, and these losses have an additive effect on AKT activation." (PMID 40227573, 2025).
leukemia (1 paper, 2023). A malignant (clonal) hematologic disorder, involving hematopoietic stem cells and characterized by the presence of primitive or atypical myeloid or lymphoid cells in the bone marrow and the blood.
liver diseases (1 paper, 2021). "Hepatic expression levels of PHLDA3 were elevated in patients with liver diseases (e.g., HCV-infected hepatitis, HBV-associated acute liver failure, and liver fibrosis), which was validated in mice models with liver injury." (PMID 33567666, 2021). "The fact that PHLDA3 can be found in urine raises its value as a potential diagnostic and/or prognostic biomarker, and suggests that it has potential as a new therapeutic target for liver diseases that are exacerbated by ER stress." (PMID 33567666, 2021). "Additional investigation may reveal further details concerning the role of PHLDA3 in various liver diseases associated with ER stress." (PMID 33567666, 2021).
lobular breast cancer (1 paper, 2024).
myocardial ischemia (1 paper, 2025). A disorder of cardiac function caused by insufficient blood flow to the muscle tissue of the heart. "Additionally, PHLDA3 inhibition protects against myocardial ischemia/reperfusion injury by attenuating oxidative stress and inflammation via the Akt/Nrf2 axis." (PMID 41289299, 2025).
papilloma (1 paper, 2025). A benign epithelial neoplasm that projects above the surrounding epithelial surface and consists of villous or arborescent outgrowths of fibrovascular stroma.
radiation-induced brain injury (1 paper, 2025). An injury to the brain which results results from exposure to radiation. "In this study, we systematically identified 35 differentially expressed proteins, including PHLDA3 and MT1M, using a rat model of radiation-induced brain injury, coupled with TMT-tagged quantitative proteomics and high-resolution mass spectrometry." (PMID 41289299, 2025).
rectal cancer (1 paper, 2017). A primary or metastatic malignant neoplasm that affects the rectum. "PHLDA3 expression was decreased in breast and rectal cancer." (PMID 28258440, 2017).
thymic lymphomas (1 paper, 2023). "Although mechanisms underlying this phenomenon remain to be further investigated, these data suggest similar processes during thymic lymphomas development between Phlda3+/− and Phlda3−/− mice." (PMID 37558703, 2023). "Collectively, our findings using Phlda3 knockout mice demonstrate that loss of Phlda3 does not alter development of acute hematopoietic injury and thymic lymphoma induced by TBI." (PMID 37558703, 2023). "Together, our findings demonstrate that loss of Phlda3 does not alter the formation of radiation-induced thymic lymphoma in mice." (PMID 37558703, 2023). "Thus, it warrants further investigations to examine alterations of gene-specific and global methylation among thymic lymphomas in irradiated Phlda3+/+, Phlda3+/− and Phlda3−/− mice." (PMID 37558703, 2023). "Moreover, we did not detect any somatic mutations in the Phlda3 gene among all murine thymic lymphomas we examined." (PMID 37558703, 2023). "Together, our results indicate that although deletion of Phlda3 does not accelerate the development of radiation-induced thymic lymphoma, fewer SNVs and indels are necessary to initiate lymphomagenesis after radiation exposure when Phlda3 is silenced." (PMID 37558703, 2023). "However, our results showed that the incidence and latency of radiation-induced thymic lymphoma were not statistically different among Phlda3+/+, Phlda3+/− and Phlda3−/− littermates." (PMID 37558703, 2023).
type 1 diabetes (1 paper, 2019). "In NOD mice, a model of type 1 diabetes, we found a significant upregulation of Phlda3 mRNA levels in comparison to control Balb/c mice." (PMID 31492921, 2019). "Interestingly, in mouse islets, Phlda3 mRNA levels were markedly upregulated in the type 2 diabetes model, but displayed comparatively modest induction in the type 1 diabetes model." (PMID 31492921, 2019).
type 2 diabetes (1 paper, 2019). "To explore the mechanism(s) underlying Phlda3 induction in type 1 and type 2 diabetes, we exposed MIN6 cells and isolated mouse islets to factors that characterize the diabetic milieu, including proinflammatory cytokines and saturated free fatty acids." (PMID 31492921, 2019). "The mRNA levels of Phlda3 were markedly upregulated in the islets of db/db mice, a model of type 2 diabetes, in comparison to age-matched lean control C57BL/KsJ mice." (PMID 31492921, 2019). "In humans, the mRNA levels of Phlda3 were markedly upregulated in the islets of type 2 diabetes donors in comparison to control subjects." (PMID 31492921, 2019).
tumor (29 papers, 2009 to 2026). "Accumulating studies have identified PHLDA3 as a vital tumor suppressor gene that is linked to tumorigenesis, disease progress along with poor prognosis in various human cancers." (PMID 35112982, 2022). "We also have showed that functional loss of PHLDA3 in PanNETs correlates with higher malignant tumor progression and poorer patient prognosis." (PMID 32521808, 2020). "In our studies, we have shown that PHLDA3 is a tumor suppressor of human PanNETs, and loss of PHLDA3 function is achieved by 2-hit inactivation in PanNETs, i.e., LOH and methylation." (PMID 32521808, 2020). "Our previous study revealed that PHLDA3 is a tumor suppressor, inactivation of which causes the development of pNET through the upregulation of the PIP3 / Akt signaling pathway." (PMID 29121094, 2017). "PHLDA3 may have a function in tumor suppression as the loss of the PHLDA3 chromosomal locus is frequently seen in primary lung tumors." (PMID 38921000, 2024). "However, PHLDA3 was only associated with the infiltration level of a small number of tumor-infiltrating cells, indicating its limited immunomodulatory role in PAAD." (PMID 36142223, 2022). "We also discuss the role of PHLDA3 as a tumor suppressor in various NETs and speculate on the possibility that loss of PHLDA3 function may be a useful prognostic marker for NET patients indicating particular drug therapies." (PMID 32521808, 2020). "PHLDA3’s tumor-suppressive function involves inhibiting the PI3K/AKT signaling pathway, which is crucial in EMT and cancer cell proliferation." (PMID 40227573, 2025). "Studies have shown that hypermethylation of CpG islands within the PHLDA3 promoter region leads to transcriptional silencing, contributing to tumor progression." (PMID 40227573, 2025). "Given the increasing prevalence of cancer worldwide, understanding the underlying mechanisms of the disease, including the potential role of PHLDA3 as a tumor-suppressor gene, is critically important." (PMID 40227573, 2025). "Analysis of the role of PHLDA3 in cSCC has revealed its significant impact on tumor progression, including metastasis." (PMID 40227573, 2025). "In PanNETs, LOH at the PHLDA3 locus correlates with higher malignancy and poorer prognosis, emphasizing PHLDA3’s critical role in suppressing tumor progression." (PMID 40227573, 2025). "Reduced PHLDA3 expression in ESCC is associated with poor patient survival and increased risk of postoperative tumor progression and recurrence." (PMID 40227573, 2025). "Unsurprisingly, a notable pattern of elevated PHLDA1, PHLDA2 and PHLDA3 expression in tumor tissues was observed in both GSE40435 and GSE53757 (all p < 0.05)." (PMID 39033192, 2024). "To confirm the tumor-suppressive role of PHLDA3, we assessed its effect on chemoresistance in OS cells." (PMID 35112982, 2022).
tumor (continued). "We therefore regard PHLDA3 as a common tumor suppressor of various NETs, although analysis of NETs from other neuroendocrine tissues is still required to be conclusive." (PMID 32521808, 2020). "We next examined the relationship between LOH at the PHLDA3 gene locus, tumor malignancy, and patient prognosis." (PMID 32521808, 2020). "Inactivation of MEN1, another well-known tumor suppressor of pNETs, together with of PHLDA3 is necessary for the development of pNET." (PMID 29121094, 2017). "As a PH domain-only protein, PHLDA3 suppresses Akt activity by competing with Akt for binding to membrane lipids and functions as a tumour suppressor in pancreatic neuroendocrine tumours." (PMID 28008906, 2016). "Co-targeting the PI3K/AKT pathway alongside strategies to boost PHLDA3 levels may yield synergistic effects, and exploring its role in immuno-oncology could provide new insights into tumor immune evasion and response to immunotherapy." (PMID 40227573, 2025). "Furthermore, low PHLDA3 expression correlates with poor prognosis in ESCC patients, including increased risk of postoperative tumor progression and recurrence." (PMID 40227573, 2025). "Moreover, many studies have reported the tumor-suppressive effects of PHLDA3 in various cancer types." (PMID 40227573, 2025). "Therefore, PHLDA3 protein significantly contributes to cellular signaling and tumor suppression as a consequence of its specific membrane lipid binding through its PH domain." (PMID 40227573, 2025). "These upregulated genes (Cdkn1a, Eda2r and Phlda3), are known for their role in cell cycle arrest, apoptosis and tumor suppression, while the most downregulated genes (Hba-a2, Serpina9, and Ms4a1) are associated with hemoglobin synthesis, mitochondrial function and B cell differentiation 34–43." (PMID 36604457, 2023). "PHLDA3 silencing greatly increased the tumor weight of mice." (PMID 35112982, 2022). "Notably, several genes related to matrix composition and immune cell recruitment were upregulated in squamous cells (Anxa1, Ecm1, Il1rn, Itgb4), as well as genes that are reported to be tumor suppressors (Serpin5b, Phlda3)." (PMID 35600339, 2022). "This indicates that PHLDA3 has an important function in tumor suppression in rectal NETs." (PMID 32521808, 2020). "Thus, further study is required to evaluate the clinical utility of PHLDA3 LOH in predicting tumor behavior." (PMID 30787304, 2019). "While PHLDA3 is known as a suppressor of neuroendocrine tumorigenicity, its deficiency has been shown to increase islet proliferation, prevent apoptosis, and enhance insulin-releasing functions without leading to tumor formation." (PMID 40227573, 2025). "Hence, our findings also revealed that PHLDA3 is a tumor repressor gene in OS and elevated PHLDA3 may be beneficial to decrease tumor size and clinical nursing of patients with OS." (PMID 35112982, 2022).
tumor (continued). "Additionally, PHLDA3, a protein of the pleckstrin homology-like domain family A, can suppress Akt activity as a dominant-negative regulator of Akt and play a prominent role in tumour suppression." (PMID 28008906, 2016). "Similarly, PHLDA-3 (Pleckstrin homology-like domain family A member 3) is a tumor suppressor gene recently discovered in PanNET, and described to be associated to worse clinical outcomes by decreased expression secondary to loss of heterozygosity (LOH) and methylation." (PMID 26894863, 2016). "PHLDA3 acts as a key inhibitor of the epithelial–mesenchymal transition (EMT) and tumor progression, including metastasis, by modulating the Phosphoinositide 3-kinases/Protein kinase B (PI3K/AKT) signaling pathway." (PMID 40227573, 2025). "Like PanNETs, LOH events at both PHLDA3 and MEN1 frequently co-occurred, indicating these genes function in distinct tumor-suppressing pathways." (PMID 40227573, 2025). "The PHLDA3 gene locus has been reported to have a high frequency of LOH in PanNETs and correlate with tumor progression." (PMID 32521808, 2020). "It is nortworthy that in pancreatic endocrine tissue, PHLDA3 acts as a tumor suppressor, and methylation and/or LOH of PHLDA3 activates Akt-regulated biological processes." (PMID 30787304, 2019). "On the other hand, four genes (ANKRD11, PHLDA3, APOL1 and MSX1) are known as tumour-suppressor factors." (PMID 19826427, 2009). "Overexpression of PHLDA3 in these cells resulted in a deceleration of their growth, a reduction in their division rate, and inhibition of the EMT process, all of which play crucial roles in tumor progression." (PMID 40227573, 2025). "Future studies should explore how PHLDA3 exerts its oncogenic effects in specific cancer subtypes and whether it can be selectively targeted to suppress tumor growth without promoting malignancy in other contexts." (PMID 40227573, 2025). "Interestingly, PHLDA3 does not always act as a tumor suppressor, as its function can vary depending on context and its interactions with other signaling pathways." (PMID 40227573, 2025). "6-AN treatment could not inhibit PHLDA3 knockout xenograft tumor growth in vivo, most likely due to the constitutively activated AKT pathway." (PMID 32312982, 2020). "Furthermore, although PHLDA3 acts as a tumor suppressor gene, knockout of PHLDA3 by itself is not oncogenic and does not generate pNETs." (PMID 29121094, 2017). "Interestingly, LOH at the PHLDA3 and MEN1 loci were not mutually exclusive, as would be expected if PHLDA3 and MEN1 were on the same tumor-suppressing pathway." (PMID 32521808, 2020).